CXCL10 (C-X-C motif chemokine ligand 10)
Diseases named in the same sentence as CXCL10 in open-access papers (continued):
Sharing a sentence is not in itself a finding about the gene and the disease.
neurosyphilis (continued). "Consistent with the antibody array data, the levels of CSF CXCL13, CXCL8 and CXCL10 were 45.9 (ranged from 0.09 to 341.42), 4.3 (ranged from 0.43 to 31.96), 7.2 (ranged from 0.37 to 67.16) fold higher in neurosyphilis patients than those in non-neurosyphilis patients, respectively." (PMID 27650493, 2016). "We hope to further evaluate the specificity of CXCL13, CXCL10 and CXCL8 in the diagnosis of neurosyphilis, so that NS can be independently diagnosed without interference from other factors." (PMID 41221293, 2025). "Our findings also show that the analysis of the chemokines CXCL13, CXCL10 and CXCL8 in the CSF can indicate the occurrence of neuroinflammation in patients who do not meet the criteria for being diagnosed with neurosyphilis." (PMID 38983560, 2022). "The HIV-positive group had higher levels of CXCL13, CXCL10 and CXCL8, but this was not statistically influenced by the neurosyphilis status in these patients with ocular syphilis." (PMID 38983560, 2022). "Antibody array analysis showed that the CSF levels of CCL24 (P = .0185), CXCL7 (P < .0001), CXCL13 (P < .0001), CXCL10 (P < .0001), and CXCL8 (P < .0001) were significantly higher in patients with than without neurosyphilis." (PMID 32419252, 2020). "We found that the levels of CXCL13, CCL24, CXCL8, CXCL10, and CXCL7 were significantly higher in the CSF of those with than those without neurosyphilis." (PMID 32419252, 2020). "In patients with ocular syphilis and neurosyphilis the AH/serum ratio for CXCL13, CXCL10 and CXCL8 was 3.78, 89.72 and 24.92 respectively while in patients with ocular syphilis without neurosyphilis the AH/serum ratio for CXCL13, CXCL10 and CXCL8 was 2.82, 76.89 and 14.04 respectively." (PMID 38983560, 2022).
osteosarcoma (9 papers, 2017 to 2025). A usually aggressive malignant bone-forming mesenchymal neoplasm, predominantly affecting adolescents and young adults. "The C-X-C motif chemokine ligand 10 (CXCL10) is implicated in the progression of osteosarcoma (OS), the most aggressive pediatric bone malignancy." (PMID 41516196, 2025). "We found that, in contrast to our parallel analyses of osteosarcomas, the mechanism of macrophage-driven immune infiltration in Ewing sarcoma was less dependent on CXCL10/CXCL12 than in osteosarcoma." (PMID 40858520, 2025). "In the present work, we first identified the relationship between c-Myc inhibition and upregulation of CCL5, CXCL9, and CXCL10 in osteosarcoma." (PMID 35292660, 2022). "The results showed that there were significant negative correlations between the c-Myc expression level and those of CCL5, CXCL9, and CXCL10 in human osteosarcoma samples." (PMID 35292660, 2022). "According to our result, high expression of CXCL10 in osteosarcoma tissues predicted a better survival." (PMID 32974202, 2020). "Similarly, a study was also reported that high circulating levels of CXCL10 are a biomarker for worse survival in osteosarcoma." (PMID 32974202, 2020). "However, we found that high expression levels of CCL5 and CXCL10 were associated with improved survival in patients with osteosarcoma, although the association for CXCL10 was not considered statistically significant (p = 0.0597)." (PMID 35292660, 2022). "Collectively, these results suggested that c-Myc inhibition can promote the regression of osteosarcoma by increasing the expression and secretion of CCL5, CXCL9, and CXCL10 in tumor tissues." (PMID 35292660, 2022). "The integrated bioinformatics analysis was utilized to provide new insight into osteosarcoma development and metastasis and identified EGR1, CXCL10, MYC, and CXCR4 as potential biomarkers for prognosis of osteosarcoma." (PMID 32974202, 2020). "The results demonstrated that gene changes of CXCL10 (P = 0.044), GNAI1 (P = 0.048), MYC (P = 0.011), and OAS1 (P = 0.0091) were significantly correlated with the overall survival of osteosarcoma patients." (PMID 32974202, 2020). "Furthermore, our work demonstrated that pharmacological inhibition of c-Myc in osteosarcoma can promote T cell trafficking into tumor beds by increasing the expression and secretion of CCL5, CXCL9, and CXCL10." (PMID 35292660, 2022). "Given that the expression of CCL5, CXCL9, and CXCL10 could be upregulated by a c-Myc inhibitor in the K7M2 model, we then asked whether this regulatory relationship also existed in human osteosarcoma." (PMID 35292660, 2022).
triple-negative breast carcinoma (9 papers, 2020 to 2026). An invasive breast carcinoma which is negative for expression of estrogen receptor (ER), progesterone receptor (PR), and human epidermal growth factor receptor 2 (HER2). "A similar finding is observed in triple-negative breast cancer where CXCL10 expression is related to a favourable prognosis." (PMID 38744099, 2024). "Evidence from both papillary thyroid carcinoma and triple-negative breast cancer suggests that elevated CXCL10 expression consistently correlates with improved prognosis, likely reflecting its role in promoting antitumor immune responses across distinct tumor types." (PMID 41476984, 2025). "Here, we identify the interferon-inducible chemokine CXCL10 and its receptor CXCR3 as key regulators of immunological dormancy in triple-negative breast cancer (TNBC)." (PMID 41617729, 2026). "Pantelidou and colleagues showed that in a cGAS-proficient model of triple-negative breast cancer, silencing of STING abrogates CXCL-10 upregulation following olaparib treatment." (PMID 39851178, 2025). "It has been shown that in CM cells, clofarabine (Clo) induces GSDME-mediated apoptosis by activating T cell immunity through CCL5 and CXCL10, and FAK-mediated phosphorylation of GRB7 plays a key role in triple-negative breast cancer (TNBC) cell migration." (PMID 41216288, 2025). "Recently, it has been shown that LSD1 inhibition in triple negative breast cancer cell lines induces expression of CD8+ T cell-attracting chemokines, including CCL5, CXCL9, and CXCL10." (PMID 32649682, 2020).
acute kidney injury (8 papers, 2015 to 2025). Sudden and sustained deterioration of the kidney function characterized by decreased glomerular filtration rate, increased serum creatinine or oliguria. "Recent reports have shown that CXCL10 is involved in the pathological processes of diverse human kidney diseases, such as mesangial proliferative glomerulonephritis (MesPGN), acute kidney injury (AKI), and nephrotoxic nephritis." (PMID 32089645, 2020). "Similarly, patients who developed acute kidney injury (AKI) requiring CRRT had elevated baseline concentrations of CXCL10 (Δ = 3236, 95% CI 1014–5459), IL-10 (Δ = 48.6, 95% CI 34–63), IL-8 (Δ = 39.9, 95% CI 17.7–62.1) and IL-6 (Δ = 1441, 95% CI 125–2697)." (PMID 40869413, 2025).
brain tumor (8 papers, 2012 to 2025). "Our results indicate increased T cell-recruiting/activating cytokines CXCL10 and CCL2 both in serum and the brain tumor milieu." (PMID 36959214, 2023). "In the brain tumors, CD169+ macrophages produced proinflammatory chemokines, such as CXCL10 and CCL5." (PMID 36266311, 2022). "CXCL10 and CXCR3 stimulate DNA synthesis and cell proliferation in vitro, suggesting that this chemokine could play an important role in brain tumor biology." (PMID 26506595, 2016).
cognitive decline (8 papers, 2018 to 2025). "This knowledge could help us to design more effective strategies to treat AD by targeting the IFN response or its downstream effector CXCL10 that are upstream of myelination deficits, an early event in AD pathogenesis that proceeds before cognitive decline." (PMID 37494190, 2023).
cystitis (8 papers, 2008 to 2024). Inflammation of the urinary bladder. "The cystitis was associated with enhanced bladder mRNA expression levels of the inflammatory cytokines, Cxcl10, Ccl2, Il18, Tgfb, and Tnfa." (PMID 35647939, 2023). "CXCL10 mRNA expression in male detrusor with acute (4 h) cystitis and intermediate (48 h) cystitis was significantly greater than that following chronic CYP-induced cystitis." (PMID 29681802, 2018). "In these studies, anti-CXCL10 antibody treatment ameliorated the severity of cystitis as determined with histological evaluation of urinary bladder and changes in leukocyte subpopulations and mast cells." (PMID 29681802, 2018). "In contrast, CXC mRNA transcript expression changes in male mice with cystitis were primarily decreases in expression (CXCL9-11) in the urothelium but both increases (CXCL10) and decreases (CXCL9, CXCL11) in expression were observed in the detrusor." (PMID 29681802, 2018). "CXCL10 mRNA expression in male urothelium with acute (4 h) and chronic cystitis was significantly (p ≤ 0.01) decreased compared to intermediate (48 h) CYP-induced cystitis." (PMID 29681802, 2018). "Neutrophils have the capacity to release CXCL10 and increase the concentration of neutrophil elastase in the urine of cystitis patients." (PMID 24278169, 2013). "We have also shown that anti-CXCL10 antibody (Ab) treatment abrogates the development of CYP-induced cystitis in mice." (PMID 24278169, 2013). "Histological differences between control Ab- and anti-CXCL10 Ab-treated mice with CYP-induced cystitis were scored and considered significant when p < 0.01." (PMID 18957084, 2008). "The described study shows that anti-CXCL10 Ab therapy reduces TNF-α expression that correlates with decreased cystitis severity." (PMID 18957084, 2008). "Splenic NK cells were unchanged during cystitis, but CXCL10 blockade dramatically reduced the number of splenic and iliac lymph node NK cells that were increased during this disease." (PMID 18957084, 2008). "TNF-α is a potent inducer of CXCL10 expression by endothelial cells; this inflammatory cytokine was negatively modulated by CXCL10 blockade during CYP-induced cystitis." (PMID 18957084, 2008). "CYP-induced cystitis in mice led to substantial increases in serum levels of CXCL10 >> CXCL9 when compared with the levels in unaffected controls." (PMID 18957084, 2008). "Perhaps in association with the differences between the various forms of IC and murine CYP-induced cystitis, CXCL10 (followed by CXCL9) was higher in mice with CYP-induced cystitis, but CXCL9 (followed by CXCL10) was found to be higher in IC patients." (PMID 18957084, 2008). "While NK cell subsets have not been demonstrated to play a profound role in IC or in CYP-induced cystitis, this study shows that NK and NKT cells were associated with cystitis in mice following CYP challenge, which was partially resolved by CXCL10 blockade." (PMID 18957084, 2008). "Due to the high levels of CXCL10 observed during CYP-induced cystitis, we next treated mice with control or anti-CXCL10 Abs to determine if inhibition of this chemokine would modulate disease." (PMID 18957084, 2008). "Interestingly, a previous report showed that systemic neutralization of CXCL-10 by monoclonal antibodies ameliorated the dysfunctional voiding following chemically induced cystitis." (PMID 25991911, 2015). "CYP-induced cystitis in mice led to substantial increases in the expression of CXCL10, CXCL11, and CXCR3 mRNA by urinary bladder leukocytes as well as modest increases in the expression of CXCL9 and CXCR3 transcripts by iliac lymph node lymphocytes than compared to normal, untreated mice." (PMID 18957084, 2008). "Similarly, affected mice treated with anti-CXCL10 Ab displayed a reduction in cystitis, as noted by a decrease in urinary bladder leukocyte infiltrates." (PMID 18957084, 2008). "In short, CXCL10 blockade significantly reduced CYP-induced cystitis." (PMID 18957084, 2008).
cystitis (continued). "The present study suggests a role for CXCL10 as a mediator of leukocyte infiltration to the urinary bladder (effector site) from the iliac and peripheral lymphoid tissues (inductive sites) during cystitis." (PMID 18957084, 2008). "However, the expression of IFN-γ, IL-12p40, and TNF-α mRNAs by urinary bladder lymphocytes from mice with cystitis were significantly decreased following anti-CXCL10 Ab treatment than compared to similar cells from CYP-induced mice treated with control Ab." (PMID 18957084, 2008). "Importantly, cystitis severity was reduced when anti-CXCL10 Ab was administered during the development of CYP-induced (acute) cystitis in mice." (PMID 18957084, 2008). "qRT-PCR demonstrated significant (p ≤ 0.01) increases in CXCL10 mRNA transcript expression in the detrusor of male mice with acute (4 h) and intermediate (48 h) CYP-induced cystitis." (PMID 29681802, 2018). "qRT-PCR also demonstrated significant (p ≤ 0.01) decreases in CXCL10 mRNA transcript expression in the urothelium of male mice with acute (4 h) and chronic CYP-induced cystitis." (PMID 29681802, 2018). "qRT-PCR also demonstrated significant (p ≤ 0.01) increases in CXCL10 mRNA transcript expression in the urothelium of female mice with acute (4 h) and intermediate (48 h) CYP-induced cystitis." (PMID 29681802, 2018). "CXC mRNA transcript expression changes in female mice with cystitis were primarily increases in expression in the urothelium and detrusor for CXCL9 and CXCL10." (PMID 29681802, 2018). "qRT-PCR also demonstrated significant (p ≤ 0.01) increases in CXCL10 mRNA transcript expression in the detrusor of female mice with acute (4 h), intermediate (48 h) and chronic CYP-induced cystitis." (PMID 29681802, 2018). "The CXC chemokine family is pro-inflammatory with family members CXCL9, CXCL10, CXCL11, and their common receptor, CXCR3, contributing to urinary bladder inflammation." (PMID 29681802, 2018). "Overall, this study suggests that CXCL10 is a mediator of CD4+ T cell, mast cell, and neutrophil infiltration to the urinary bladder (effector) during cystitis." (PMID 24278169, 2013). "Together, these results indicate that CXCL10 blockade modulates the number of systemic and mucosal NK cell subsets that are altered during CYP-induced cystitis." (PMID 18957084, 2008). "In summary, mice with CYP-induced cystitis expressed higher serum CXCL10 > CXCL9 than unaffected controls, while IC patients displayed higher CXCL9 > CXCL10 serum levels than unaffected individuals." (PMID 18957084, 2008). "We also demonstrate for the first time that anti-CXCL10 Ab treatment prevents the development and onset of CYP-induced cystitis." (PMID 18957084, 2008). "CXCL10 mRNA expression in female urothelium with acute (4 h) cystitis was significantly (p ≤ 0.01) greater than that with intermediate (48 h) and chronic CYP-induced cystitis." (PMID 29681802, 2018). "CXCL10 mRNA expression in female detrusor with acute (4 h) cystitis was significantly (p ≤ 0.01) greater than that with intermediate (48 h) and chronic CYP-induced cystitis." (PMID 29681802, 2018). "Histological evaluations of mice with or without EAC-induced cystitis after control and/or anti-CXCL10 Abs treatment." (PMID 24278169, 2013). "Despite the reduction of serum CXCL9 and CXCL10 levels following anti-CXCL10 Ab treatment(s) of mice given CYP, it remained uncertain whether CXCL10 blockade would improve the pathology of cystitis." (PMID 18957084, 2008). "Because of the high levels of CXCL10 observed during EAC, we next treated these mice with control or anti-CXCL10 Ab to determine whether inhibition of this chemokine ligand would modulate the severity of cystitis." (PMID 24278169, 2013). "Antibody (Ab)-mediated inhibition of the most abundant serum CXCR3 ligand, CXCL10, in mice decreased the local production of CXCR3 ligands as well as Th1 cytokines expressed by local leukocytes, and lowered corresponding serum levels to reduce the severity of CYP-induced cystitis." (PMID 18957084, 2008).
cystitis (continued). "Hence, the current study suggests CXCL10 is partially responsible for changes in the distribution of CXCR3+ Th1 cells, mast cells, and NKT cells from the spleen and iliac lymph nodes to the urinary bladder after CYP treatment, which corresponded with cystitis." (PMID 18957084, 2008). "The presence of anti-CXCL10 Ab might hinder the movement of these CXCR3+ T cells that would otherwise migrate to the urinary bladder and/or iliac lymph nodes to exacerbate CYP-induced cystitis." (PMID 18957084, 2008). "Our results show that CXCL10 blockade does not affect the percentage of CD4+ T cells in the spleen of naïve mice, but inhibition of CXCL10 in CYP-treated mice with cystitis lead to an increase in the percentage of T helper splenocytes." (PMID 18957084, 2008).
dry eye (8 papers, 2010 to 2025). "Activation of the cGAS-STING pathway induced the expression of CXCL10, IL-6 and IFN-β, which were reported to be increased in dry eye patients and dry eye mice, and CXCL10 could potentially serve as a biomarker of dry eye." (PMID 37735446, 2023). "For example, in dry eye mouse models, bacterial lipopolysaccharides (LPS) increases the expression of inflammatory mediators including IL-1β, IL-6, CXCL10, IL-12a, and IFN-γ in the conjunctiva and IL-1β and CXCL10 in the cornea." (PMID 38983562, 2022). "Also, increased levels of CXCR3 ligands—CXCL9, CXCL-10 andCXCL-11—were detected in tears of patients with pSS compared with those of patients with non-Sjögren’s dry eye." (PMID 37893153, 2023).
esophageal cancer (8 papers, 2013 to 2025). A primary or metastatic malignant neoplasm involving the esophagus. "Two chemokines (CCL11 and CXCL10) in posttherapeutic tumor tissue were associated with prognosis in patients with esophageal cancer, lower levels indicating a better prognosis." (PMID 28537901, 2017). "In this study two chemokines (CCL11 and CXCL10) in the posttherapeutic tumor tissue were associated with prognosis in patients with esophageal cancer." (PMID 28537901, 2017). "In summary, our study highlights the critical role of immune infiltration intensity and its molecular determinant — CXCL10 in shaping the efficacy of neoadjuvant immunotherapy for esophageal cancer." (PMID 40574841, 2025). "This highlights the potential utility of CXCL10 expression as a biomarker for predicting treatment response and guiding personalized therapeutic strategies in esophageal cancer." (PMID 40574841, 2025). "Based on our findings, we propose that CXCL10 could serve as a potential prognostic marker to guide therapeutic interventions for esophageal cancer." (PMID 40574841, 2025). "In addition histopathological responders had lower CXCL10 serum levels than nonresponders, emphasizing its potential role in esophageal cancer." (PMID 28537901, 2017).
head and neck cancer (8 papers, 2018 to 2025). A primary or metastatic malignant neoplasm affecting the head and neck. "CXCL10 (also known as IP-10) is an inflammatory cytokine, recruiting leukocytes and stimulating osteoclastogenesis and has been implicated in various diseases, such as RA, autoimmune, and head/neck cancers." (PMID 39125970, 2024). "In vivo, cetuximab treatment enhanced the serum levels of CXCL9 and CXCL10 in patients with head and neck cancer." (PMID 30192802, 2018). "In this study, we analyzed the immune regulatory properties of EGFR signaling in head and neck cancer cells and showed that it suppresses type 1 cytokine-induced expression of CCL2, CCL5, CXCL9, CXCL10 and IL-6 while promoting the expression of IL-1β." (PMID 30192802, 2018).